MYC (MYC proto-oncogene, bHLH transcription factor)
Diseases named in the same sentence as MYC in open-access papers (continued):
Sharing a sentence is not in itself a finding about the gene and the disease.
tumor (continued). "Immunofluorescence staining performed on three of these mHNcSCC samples demonstrated expression of c-MYC on cells within the tumor nests (TNs) and the peri-tumoral stroma (PTS) that also expressed KLF4." (PMID 32850316, 2020). "A recent study demonstrated that CDK9-specific inhibitor, MC180295, downregulates MYC and leads to reactivation of epigenetically silenced tumor suppressor genes." (PMID 33322239, 2020). "Upon MYC inactivation, these signals are lost, and significant tumor regression is seen, confirming the relevant role of MYC in opposing anti-tumor immunity." (PMID 33081056, 2020). "Following MYC inactivation, tumors undergo various proliferative arrests, cell differentiation, and apoptosis, thus inhibiting tumor occurrence." (PMID 33115513, 2020). "Among the top pathways, including 31 activated in at least four tumor types, we observed a strong impact of CTNNB1 as well as several other pathways described in the literature as influencing anti-tumor immunity such as MYC, PPARG and SHH (sonic hedgehog)." (PMID 33106165, 2020). "It is worth noting that MYC effects on tumor metabolism are strictly dependent on the cancer’s tissue of origin." (PMID 32932943, 2020). "Conversely, the inactivation of MYC and Twist1 in tumors shows rapid and complete tumor regression in all observed mice (n = 20) within 2 weeks and also prompt exodus of macrophages." (PMID 31933479, 2020). "Another player regulated by MYC in tumor microenvironment that has a distinct role in tumor angiogenesis is matrix metallopeptidase 9 (MMP-9)." (PMID 33081056, 2020). "dPCR for the determination of MYC copy numbers has been performed only in a small number of studies for different tumor entities." (PMID 33014186, 2020). "We then examined the tumor immune microenvironment and found that there was significant infiltration of both favorable and unfavorable immune cells in higher MYC score tumors as well as correlation of higher T helper cells." (PMID 33143224, 2020). "(F) Zoom-in-views of the SKIL and MYC amplicons in representative single-cells illustrating the heterogeneity in the level of chromosomal amplification in tumor P6." (PMID 32401198, 2020). "In a myeloid lineage MYC KO mouse model, MYC had important roles in macrophage maturation and function leading to reduced tumor growth." (PMID 32685002, 2020). "Previous studies reported that in transgenic mouse models have an insight that transient inactivation of the c-MYC leads to tumor regression." (PMID 32604971, 2020). "Genetic mutations of XPO5 leads to an entrapment and loss of precursor miRNAs in the nucleus promoting tumor initiation through an increase in the expression of stemness-related genes such as EZH2 and MYC." (PMID 32486505, 2020). "Because CDK7 is necessary for the expression of MYC, which is important for vasculogenesis and angiogenesis throughout tumor development and progression, we also studied the effects of CDK7 inhibition on angiogenesis." (PMID 32340192, 2020). "Previous studies showed that CUDC-907 and other HDAC inhibitors suppress MYC expression and inhibit MYC-dependent tumor proliferation in a variety of cancer types." (PMID 33069237, 2020). "Combinatorial efficacy was observed in MYCs-amplified and MYCs-wt SCLC cells over SCLC cells with impaired MYC signaling pathway or non-tumor cells." (PMID 33339368, 2020). "Immunofluorescence (IF) staining demonstrated an OCT4+/SOX2+/KLF4+/c-MYC+ CSC subpopulation within the tumor nests (TNs) and another within the peritumoral stroma (PTS) of HNmMM tissues." (PMID 32019273, 2020). "MYC is a master regulator of tumor energy metabolism via regulation of enzymes and transporters such as hexokinase (HK2) and glucose transporters (GLUT)." (PMID 32690037, 2020). "Results of a phase I study show a tolerable safety profile with endurable anti-tumor responses in patients with MYC overexpressing DLBCL." (PMID 33092116, 2020).
tumor (continued). "More recently, novel studies have shown that MYC plays a role not only in tumor initiation and growth but also has a broader spectrum of functions in tumor progression." (PMID 33081056, 2020). "Lastly, MYC seems to be able to successfully recruit active components of the tumor microenvironment for its needs, and EMT and metastasis formation are not an exception." (PMID 33081056, 2020). "It will also discuss the roles of MYC in regulating tumor microenvironment and metastasis formation." (PMID 33081056, 2020). "Collectively, our in vivo study suggested that combined administration of BMN673 and JQ1 induced synergistic anti-tumor effects against MYC paralog-dependent SCLC xenografts and PDX explants." (PMID 33134168, 2020). "Apart from its transcriptional regulation function, YB1 translationally activates a set of mRNAs whose protein products are involved in the process of embryonic development and tumor progression, such as Snail, twist, HIF1a and MYC." (PMID 32028981, 2020). "The analysis suggests increased expression of CD8+ T-cell, DC, and Treg function genes in 3 × 5 Gy RT-treated tumours compared to controls, suggesting “early” anti-tumour immunogenic effects post-RT in MyC-CaP as seen in TRAMP-C1." (PMID 32641865, 2020). "The data collected by the authors suggested that the best method for identifying all HGBL-DH/TH tumours is to perform FISH for the MYC rearrangement for all cases; when FISH testing is positive, BCL2 and BCL6 gene aberrations should be investigated." (PMID 31940809, 2020). "The dual-negative regulation of ZEB1/MYC is thought to be the molecular mechanism of cell plasticity, regulating the state of tumor stem cells and promoting tumor invasion and metastasis." (PMID 32014049, 2020). "Overall, these results indicate that BET inhibitor I-BET762 and PARP inhibitors have a preferential or selective combinatorial efficacy on MYCs-amplified or MYCs-wt SCLC cells over non-tumor cells or SCLC cells with an impaired MYC signaling pathway." (PMID 33339368, 2020). "Inhibition of oncogene myc expression has been characterized by the canonical effects of BETis in many tumour types, but MYC‐independent manner also existed." (PMID 32954665, 2020). "BL is characterized by MYC translocations, resulting in very rapid tumor growth, and tumor cells can quickly spread outside the lymph nodes including the central nervous system and bone marrow." (PMID 32676030, 2020). "Recently developed small molecules MYCi 361 and MYCi 975 destabilize the MYC protein and consequently inhibit tumor growth." (PMID 33092116, 2020). "Conversely, KLF10 is a tumor suppressor that represses MYC expression in healthy cells and is involved in repressing proliferation and inducing apoptosis." (PMID 32945258, 2020). "MiR-193a expression, on the other hand, led to global repression of gene expression accompanied by the tumor-suppressive effect in MYC overexpressing Group 3 cells." (PMID 32410663, 2020). "The expression of gene sets related to Wnt/β-catenin signaling, MYC target genes, E2F transcription targets, and others were enriched in tumor samples compared to normal samples." (PMID 32962010, 2020). "In this scenario, inhibition of GSK-3 resulted in increased β-catenin and c-MYC activities which abrogated KRAS-dependent tumor growth." (PMID 32365809, 2020). "In sum, a better understanding of MYC’s role in the tumor microenvironment and metastasis development is crucial in proposing novel and effective cancer treatment strategies." (PMID 33081056, 2020). "MYC is involved in a lot of different direct and indirect mechanisms of promoting angiogenesis in both cancer cells and other components of the tumor microenvironment." (PMID 33081056, 2020). "Genes associated with the SEs in tumor cells were mostly related to transcription (e.g., POLR2E, PARK7, MYC)." (PMID 33168807, 2020).
tumor (continued). "From the oncology point of view, this protein acts in cell progression, apoptosis, and tumor cell invasion processes through repression of MYC gene and activation of FAK in the PI3K/AKT pathway." (PMID 32537125, 2020). "Altogether, our data demonstrated CX-5461 has important clinical implications for the treatment of patients with olaparib-resistant OVCA and for patients with high MYC activity tumours and poor clinical outcome." (PMID 32457376, 2020). "The comparison of the status of HER2, MDM2, and c-MYC genes of the 37 GC patients’ CTC samples with that of the patients’ matched tumor tissues demonstrated that the mean interval between the CTC and tissue samples was equal to 20.1 days." (PMID 31454863, 2020). "More recently, novel studies have shown that MYC can be considered a crucial regulator of tumor microenvironment." (PMID 33081056, 2020). "One explanation for this heightened sensitivity of MYC-driven tumours to Pol I transcription inhibition is the ability of MYC to sensitise cells to NSP." (PMID 31973211, 2020). "In fact, they can induce glutaminase and LDH (lactate dehydrogenase) upregulation and a significant correlation between LDH and MYC has been reported in the tumor stroma." (PMID 32015297, 2020). "To functionally confirm that the anti-tumor effects of Arf1-depletion in Lgr5/Apc and MYC-ON mice were indeed dependent on the observed adaptive immune response, we depleted the T lymphocytes after tumor formation by injecting anti-CD4 or anti-CD8 antibodies." (PMID 31924786, 2020). "This complex relationship implies the control of MYC oncogene pathways leading to tumor development and progression." (PMID 32150871, 2020). "In summary, this research demonstrates the potential of MYC-MAX inhibition with a small molecule to affect specific changes in the tumor promoting M2 macrophage population." (PMID 32685002, 2020). "MYC also promotes tumor progression, and it is often involved in the processes of resistance to chemotherapy and metastasis." (PMID 33081056, 2020). "Our analyses in primary tumor showed that CNV in all 3 exons and CNV in the second exon of MYC were associated with unfavorable UCB features, e.g. pathologic tumor stage and MVI." (PMID 33298978, 2020). "In summary, we found m6A modification of AFF4 RNA was upregulated by METTL3 and their expression was elevated in BCSCs, which in turn promotes the expression of SOX2 and MYC to enhance tumorigenesis and tumor-initiating capacity of BCa." (PMID 32676121, 2020). "Sirt6 suppresses tumor growth mainly through suppression of anaerobic glycolysis and co-suppression of MYC, thereby inhibiting cancer occurrence and development." (PMID 32711549, 2020). "MYC-driven over-expression of these molecules suppress both innate and adaptive immune responses favoring tumor progression." (PMID 33081056, 2020). "Contrarily, MYC was normoexpressed only in the tumours of the corticotroph line (both functioning and silent corticotroph tumours) and repressed in the other subtypes (GTs and STs)." (PMID 32316225, 2020). "It is reported that activated fibroblasts secrete increased levels of ECM-degrading proteases such as MMP2, MMP3, and MMP9, which are very important for tumor invasiveness and are potentially regulated by MYC." (PMID 33081056, 2020). "MYC impacts many facets of tumor cell metabolism, such as glycolysis, glutaminolysis, and lipid and nucleotide synthesis, and thus affords metabolic flexibility to cancer cells in unfavorable conditions." (PMID 32138178, 2020). "In contrast, upon NUAK1 inhibition in MYC-driven tumor cells termination is suppressed and RNAPII is trapped in a form that is not involved in productive transcription." (PMID 32006464, 2020). "There are no previous studies addressing the possible role of these MYC+ and MYC− macrophages in human tumor models." (PMID 32523087, 2020).
tumor (continued). "The notion that deregulated expression of MYC strongly sensitizes tumor cells toward a wide range of pro-apoptotic stimuli is considered a mechanism that protects from tumorigenesis." (PMID 32006464, 2020). "FBW7 degrades some proto‐oncogenes that play a role in cell growth and division pathways, including JUN, Notch, MYC and cyclin E.47FBW7 is also a tumour suppressor and its regulatory network is disrupted in many human malignancies." (PMID 32352219, 2020). "In the primary tumor, 15 (35.7%), 11 (26.2%), 4 (9.5%) and 4 (9.5%) patients harbored amplifications in all 3 exons of MYC, CCND1, ERBB2 and CCNE1, respectively." (PMID 33298978, 2020). "To perform our studies, we have generated the first autochthonous transgenic mouse model of HCC metastasis by hepatocyte-specific expression of MYC and Twist1 that will be useful to study tumor progression and identify new therapies." (PMID 31933479, 2020). "In our research, the upregulation of ES_HPCAL1 negatively affected tumor prognosis (HR > 1), but the MYC repression pathway was significantly enriched in the functional analysis." (PMID 32282333, 2020). "MYC is a highly pleiotropic transcription factor whose aberrant activation links tightly with tumour progression, including both cell‐intrinsic proliferation and extracellular microenvironment alterations such as tissue remodelling, angiogenesis and invasion." (PMID 32175651, 2020). "Genetic amplification of the oncogene c-MYC has been found to be a critical step of FL transformation via the induction of tumor growth and chromosomal instability." (PMID 33168041, 2020). "Consistent with previous publications, MYC alone resulted in multiple large tumor nodules within 6–8 weeks after injection." (PMID 32055024, 2020). "MYC DNA methylation was lower in tumor than paired normal prostate tissue for all six CpG sites (median difference: −14.74 to −0.20 percentage points), and we observed similar results for two nearby sites in The Cancer Genome Atlas (p < 0.0001)." (PMID 33374332, 2020). "Inhibitors of glutaminase or transaminase have shown the therapeutic efficacy in multiple MYC-driven tumor models, and a representative glutaminase inhibitor, CB-839, is currently under clinical trials for patient treatment." (PMID 32651356, 2020). "MM translocations juxtapose highly expressed immunoglobulin loci (IGH, IGK, and IGL) with oncogenes such as WHSC1 and MYC, leading to upregulation and tumor selective advantage." (PMID 32471990, 2020). "Since the hyperstimulation of the cell cycle is vital in the process of neoplasia development, MYC overexpression is commonly detected in human tumors." (PMID 32971884, 2020). "In contrast, in malignant cells, PVT1 promoter was inactive due to epigenetic silencing or structural variation, and thus restored the enhancer–promoter looping for MYC, thereby increasing MYC expression and tumour growth." (PMID 32941624, 2020). "MYC is a famous oncogene which overexpresses in many tumors and plays a critical role in tumorigenesis and tumor proliferation, apoptosis." (PMID 32700728, 2020). "Overall, H3.3K27M mouse tumours show similar mutation patterns to human DIPG, with frequent mutations in the RAS/MAPK/PI3K pathway (50%) and MYC (20%)." (PMID 33277484, 2020). "Reports show that KRAS and MYC collaborate in shaping the tumor microenvironment and work together to support tumor growth while avoiding immune recognition." (PMID 33081056, 2020). "In young-PD patients ERG/MYC/NEDD4L/MAOA oncogene panel was found to be activated whereas in old-PD patients HLA-A/B/ANXA2/LDHB/ID4 tumor suppressor panel was down regulated." (PMID 33575208, 2020). "The PERK-ATF4 pathway induces autophagy in MYC-induced lymphoma and support the transformation process and tumour growth." (PMID 32111004, 2020).
tumor (continued). "Over the years, published reports unarguably demonstrated a crucial role for MYC in creating a favorable immunosuppressive tumor microenvironment through different mechanisms, depending on the tumor type, the tissue, and the surrounding microenvironment." (PMID 33081056, 2020). "Various studies reported that miR-26a acts as a tumor suppressor by downregulating c-MYC pathway, cAMP regulated phosphoprotein 19 (ARPP19), HOXC9." (PMID 32512882, 2020). "MYC proteins drive an increased cellular proliferation and facilitate multiple aspects of tumor initiation and progression, thereby controlling all hallmarks of cancer." (PMID 32832554, 2020). "Many of the client proteins regulated by HSP90AA1 are proto-oncogene products (such as c-MYC) or important signal transduction factors during tumor pathogenesis, which are closely related to the occurrence and development of tumors." (PMID 32576198, 2020). "(h) Quantification of F4/80 staining in early tumor vs late tumor vs regressed MYC/Twist1-HCC (**p<0.01)." (PMID 31933479, 2020). "This will allow uncontrolled effects of MYC overexpression and activation leading to rapid proliferation and tumor formation." (PMID 33585252, 2020). "Instead, metastatic progression was dependent on the ability of MYC and Twist1 to dramatically reprogram the tumor innate immune microenvironment." (PMID 31933479, 2020). "We are presenting compelling evidence that the haploinsufficient tumor-suppressor RASSF10 can be used as a prognostic and diagnostic cancer biomarker in combination with other tumor related genes (e.g., MYC) in kidney diseases." (PMID 32047266, 2020). "For MYC, tumor samples obtained from advanced and early stage diseases had an amplification rate of 33% and 14%, respectively (p = 0.023)." (PMID 32877461, 2020). "In MYC-overexpressing tumours, NUAK1 reduces metabolic stress by inhibiting mTORC1 and sustaining glutamine metabolism." (PMID 32429240, 2020). "A high expression of the proto-oncogene c-MYC has long been identified as a key factor in neoplastic transformation for many tumor types." (PMID 31861163, 2019). "In patients with DHL/THL, the cooperation between BCL2-induced inhibition of apoptosis and MYC-induced genomic instability promotes oncogenesis and tumour progression." (PMID 31315646, 2019). "The three proteasome inhibitors which downregulated MYC expression in HLRCC tumor cells, also decreased the expression of GLS and GLS2." (PMID 31804603, 2019). "Collectively, miR‐487b is regulated by DNA methylation and it functions as a tumor suppressor in CRC mainly through targeting MYC, SUZ12, and KRAS." (PMID 30791232, 2019). "In this study, we used MYC/Runx2 mice, a transgenic model displaying rapid tumor formation that is further accelerated by MLV infection." (PMID 31815961, 2019). "Inactivation of the MYC oncogene in a mouse model of T-ALL (EμSRα-tTAα;tet-o-MYC) causes sustained tumor regression by eliciting the phenomenon of oncogene addiction." (PMID 31266538, 2019). "The prior or simultaneously inactivation of apoptosis is typically a prerequisite for tumour initiation by high levels of MYC." (PMID 31032816, 2019).